IL33 (interleukin 33)
Diseases named in the same sentence as IL33 in open-access papers (continued):
Sharing a sentence is not in itself a finding about the gene and the disease.
tumor (continued). "We had previously connected low CD8 expression by cytotoxic T cells to the induction of the membrane‐bound receptor for IL‐33, suppression of tumourigenicity 2 (ST2)L14, 15; we included this receptor and IL6ST (CD130) as two promising factors for the validation of CD8Low T cells in tumour sections." (PMID 36504430, 2022). "However, further investigation is required to determine how much of the reduction in tumour burden can be attributed to a reduction in Il33 expression, rather than to a direct effect of EGFR inhibition." (PMID 36263033, 2022). "It is reported that IL-33 promoted the proliferation and activation of CD8+ T cells and NK cells through modulating the NF-κB signaling pathway, and promoted their infiltration in the tumor lung metastasis, thereby producing a significant effect of inhibiting tumor growth and lung metastasis." (PMID 35634336, 2022). "We also found evidence for increased activation and expansion of the MMC subset, based on IL-33 dependent expression of selective markers, Mcpt1 and Mcpt2, within gp130F/F antral stomachs, and enrichment specifically within CD45+ cell fractions isolated from tumours by flow sorting." (PMID 35677533, 2022). "Interestingly, this phenomenon is not observed in Treg cells within the tumor microenvironment; intratumoral Treg cells need intranuclear IL-33 to shape their transcriptional landscape and maintain their suppressive properties." (PMID 35979357, 2022). "Tumor-derived factors such as colony-stimulating factor 1 (CSF1; also known as M-CSF), granulocyte-macrophage colony-stimulating factor (GM-CSF), CC-chemokine ligand 2 (CCL2), CCL7 (or MCP-3), GDNF, IL-33, CXCL12 (SDF-1) and EGF are responsible for myeloid cell recruitment and promote tumor growth." (PMID 36140392, 2022). "Therefore, to test whether decreased TNF-α and increased IL-33 do indeed lead to increased numbers of CD103+ DCs in the tumor microenvironment, we stained the tumor sections for both CD11c and CD103 and observed a significant increase in both DC markers." (PMID 36256464, 2022). "Here, our finding showed that DPP-4i promoted caspase-1-dependent processing of IL-1β and IL-33 by activating NF-кB–NLRP3 activation, indicating that DPP-4i may reprogram tumor microenvironment by promoting 4T1 cells-derived IL-1β and IL-33 via NF-кB–NLRP3 pathway." (PMID 34631556, 2021). "In addition, the accumulation, proliferation, as well as immunosuppressive activity of MDSCs were diminished in tumor-bearing mice in the absence of IL-33/ST2 signaling." (PMID 34209038, 2021). "In addition, IL-33 is released by tumor cells and by a myriad of immune and non-immune cells localized in human lung." (PMID 33445787, 2021). "Interestingly, in a PDAC mouse model, IL-33 upregulated PD-1 specifically on Tumor ILC2 but not on draining LN ILC2." (PMID 34209038, 2021). "Additionally, this research also demonstrated that IL-33 could recruit macrophages into TME and stimulate them to produce prostaglandin E2 that supported CRC stemness and tumor growth." (PMID 34063627, 2021). "Our study revealed a novel link between the levels of IL‐33 and OPN in the peripheral blood and tumor growth, thus suggesting that the two cytokines could be considered as simple and efficient biomarkers to evaluate the effectiveness of early cetuximab treatment of CRC." (PMID 34664425, 2021). "Although the mechanisms are still not clear, these discoveries suggest that IL-33 may be upregulated in hypoxic tumor microenvironments." (PMID 34298657, 2021). "High levels of IL‐33 could further bind to ST2 on NK cells, which induced increased levels of CD137 and CD107a in NK cells, as well as increasing the cytotoxicity of NK cells toward tumor cells." (PMID 34664425, 2021).
tumor (continued). "In summary, not only are tumor-infiltrating cytotoxic CD8+ T lymphocytes necessarily exposed to metabolic stress due to local nutrient deprivation, but they are also influenced by immunosuppressive mediators, chemokines and bioactive IL-33 released from necrotic tumor cells." (PMID 34504486, 2021). "However, IL-33 did not demonstrate Hepa1-6 cell proliferation in vitro, excluding its direct effect on tumour cells." (PMID 33308251, 2020). "Moreover, IL-33 can act as a novel immunoadjuvant to augment vaccine-induced protective antiviral CD8+ T cell responses and thus to improve T cell responses induced by an anti-tumor DNA vaccine." (PMID 32315596, 2020). "However, as described, IL-33 play the major role in ILC2s activation since IL-25 activate only iILC2s and TLSP may trigger TSLP receptors expressed by tumor cells in an autocrine manner and independently from a type 2 inflammation." (PMID 33233582, 2020). "Moreover, the IL-33/ST2L axis is critical for Treg expansion and, therefore, it could indirectly promote tumor suppression." (PMID 33371444, 2020). "In fact, IL-33 can directly activate human and mouse eosinophils by up-regulating activation markers (i.e. CD69), adhesion molecules (i.e., ICAM-1 and CD11b/CD18), and the degranulation markers CD63 and CD107a, resulting in the killing of several tumor cell types." (PMID 33329534, 2020). "The efficacy of IL-33 may be partly attributable to tumour immunogenicity rather than to the changing intrinsic characteristics of tumour cells, as reported in literature." (PMID 33308251, 2020). "Or because of the changes of tumor microenvironment which could not be simulated in vitro leads to the weak effect of IL-33." (PMID 32003751, 2020). "However, the pathologic N stage (AJCC staging system) of the tumor did not influence the expression level of IL-33." (PMID 33634017, 2020). "The KEGG pathway enrichment analysis revealed that high IL-33 may increase the extent of malignancy of tumor cells in LSCC, which could explain the negative prognostic role of IL-33." (PMID 33634017, 2020). "Therefore, IL-33 may induce chemokines (e.g. Cxcl1), which enhanced the recruitment of myeloid cells secreting S100A9 to promote tumour progression." (PMID 33308251, 2020). "To investigate whether exogenous IL-33 affects HCC occurrence by regulating the immune system, we examined immune cell phenotypes in the spleen and tumours of Hepa1-6-bearing mice treated with IL-33 and those who were not." (PMID 33308251, 2020). "IL-33 treatment of CT26 tumor-bearing ∆dblGATA-1 mice showed no decrease in tumor size." (PMID 32923137, 2020). "However, IL-33 can induce and amplify Th2 responses in the TME, which may support tumor progression." (PMID 33329534, 2020). "In our study, we did not observe differences in IL-33 content according to the tumor stage." (PMID 31281317, 2019). "Lastly, IL-33, and to a certain extent IL-18, are liable to induce Areg production independently of the T cell receptor (TCR) (innate Treg function), thereby contributing to restorative functions, particularly those of the epitheliums, and also favoring tumor promotion and growth." (PMID 31507607, 2019). "Overall, although IL-13 production was always found to have a negative impact on the immune response, the consequences of IL-33 or IL-25 on ILC2s in a tumor may vary depending on organs or on the cellular and molecular environment." (PMID 31024531, 2019). "However, the content of sST2 is diminished in tumor tissue of CRC patients and inversely correlates with more advanced tumors, as well as IL-33 content correlation to tumor progression, suggesting that IL-33/ST2 axis participates in the progression to CRC metastasis." (PMID 31281317, 2019). "However, there are some studies that propose an antitumor role of IL-33/ST2 which might depend on the tumor microenvironment and in specific stages of tumor development and progression, as some recent comprehensive reviews have described." (PMID 31281317, 2019).
tumor (continued). "According to this data together with antecedents that attribute an anti-tumorigenic role to ST2 in murine models, we suggest that ST2 could have a protective role on early stages of tumor progression, particularly in left colon and specially soluble ST2, which might neutralize IL-33." (PMID 31281317, 2019). "Regardless of the source of IL-33, whether tumor-derived or stromal, the overall impact of IL-33/ST2 signaling lies in its ability to direct the remodeling of the TME." (PMID 30205617, 2018). "Although IL-33 has been reported to play pro-tumorigenic or anti-tumorigenic roles in cancer development, both functions implicate IL-33 as a potent modulator of the TME by playing a major role in recruiting immune cells that impact tumor phenotype and malignancy." (PMID 30205617, 2018). "Likewise, IL-33 stimulates the secretion of cytokines and growth factors in bone marrow myeloid and non-hematopoietic cells, resulting in myeloproliferation of neoplasms." (PMID 30416507, 2018). "Moreover, down-modulation of IL-33, together with down-modulation of antigen processing machinery and MHC-I-related genes during the primary to metastatic transition in tumours, represents a newly defined form of tumour immune-escape." (PMID 29440650, 2018). "In this review we will cover the biological functions of IL-33 on various immune cell subsets (e.g., T cells, NK, Treg cells, ILC2, eosinophils, neutrophils, basophils, mast cells, DCs, and macrophages) that affect anti-tumor immune responses in experimental and clinical cancers." (PMID 30483263, 2018). "Results showed that administration of IL-33sustained elevated levels of IL-33 in the serum of tumor-bearing mice, significantly increasedtumor size, andinduced the percentage of Tregs as well as ST2L+Treg cells in both spleen and tumor tissue oftumor-bearing mice." (PMID 29950152, 2018). "We show that the IL-33/ST2 interaction is necessary for SCC progression, that it is involved in a mechanism during the recruitment of CD4+ T lymphocytes, dendritic cells, and macrophages in the tumor microenvironment, and that it promotes the production of IFN-γ, TNF-α, IL-10, and IL-17." (PMID 30112116, 2018). "Furthermore, a similar increase in metastases was noted in ILC2-deficient mice for metastatic A9+IL-33 tumours, and most strikingly, for the primary TC1 tumours, which are not predisposed to form metastases in any setting previously studied." (PMID 29440650, 2018). "The expression of IL-33 has also been negatively correlated with the expression of chemokines, such as TGF-β, recruiting Treg and MDSC, and positively correlated with the expression of chemokines that recruit CD8+ T cells which promote anti-tumor immune responses especially through INF-γ production." (PMID 30416507, 2018). "Herein, we summarize the recent discoveries in understanding the critical role of the IL-33/ST2 pathway in contributing to the pathogenesis of colorectal tumorigenesis and discuss its potential implications for the future development of effective anti-tumor strategies." (PMID 30547011, 2018). "Therefore, although the exact mechanism of IL-33's promotion of CRC development is still unknown, its pro-tumor function in the colorectal mucosa is likely due to a combination of several mechanisms." (PMID 30547011, 2018). "This indicates that the tumour microenvironment is important for ILC2-mediated cancer immune-surveillance, and in particular the expression of IL-33 by the tumour may allow the activation of ILC2 function, whereas the lack of IL-33 expression would not support these immune cells." (PMID 29440650, 2018). "Strikingly, the number of ILC2s isolated from IL-33-expressing metastatic A9 tumours was more than 30-fold higher than what could be isolated from metastatic A9 tumours not expressing IL-33 in mice transplanted with WT BM." (PMID 29440650, 2018).
tumor (continued). "We next found that the largest tumours were formed from metastatic tumour cells that had little to no IL-33 expression and these corresponded to tumours from which little to no ILC2s could be isolated." (PMID 29440650, 2018). "In NSCLC tumor tissues, IL-33 is robustly expressed in cancer cells while ST2 is expressed on both cancer cells and infiltrated lymphocytes, indicating IL-33 as a dual-function factor that could affect both NSCLC cells and immune surveillance in tumor microenvironments." (PMID 28978138, 2017). "Interleukin‐33 (IL‐33), a cytokine secreted by endothelial and epithelial cells to activate NF‐κB and MAPK signalling, may also hold therapeutic interest for the reprogramming of endothelial cells and normalization of tumour vasculature in CRC." (PMID 28085225, 2017). "Not only does IL-33 appear to be important for the expression of the immune-recognizable phenotype in primary tumour cell lines, but also MHC-I and IL-33 appear to be correlated during the metastatic re-programming of primary murine lung tumour revealing the metastatic potential of IL-33 gene." (PMID 27619158, 2016). "Interestingly, the implantation of IL-33 tumour cells alone in the perivitelline space did not significantly display high dissemination." (PMID 27150562, 2016). "Overexpression of IL-33 in tumours has no impact on primary tumour growth." (PMID 27150562, 2016). "Because TAMs, CAFs, lymphocytes and tumour endothelial cells were negative for IL-33, we hypothesised that P29 cells themselves were induced to express a higher level of IL-33 by some kinds of factors in vivo." (PMID 26775708, 2016). "However, at present, we cannot explain the reason why not all P29 cells in the tumours expressed IL-33." (PMID 26775708, 2016). "Similarly, Ccl2 expression is not decreased in Panc02 tumours implanted in St2−/− and Il33−/− mice compared with those in wt mice as validated by qPCR." (PMID 27150562, 2016). "Furthermore, IL-33 has been reported to be expressed in endothelial cells in normal organs, but not in tumor tissues." (PMID 24959294, 2014). "However, IL-33 neutralisation in vivo led to a more quiescent tumour characterised by the infiltration of CD4+ T cells producing interferon gamma (IFNγ) (Th1-like) and decreased Th2-like cells (CD8+ and CD4+ T cells expressing IL-4) in the tumour microenvironment." (PMID 38662248, 2024). "Collectively, these findings suggest that the absence of IL-33 within tumor tissues promotes an accelerated rate of tumor growth and is accompanied by a downregulation of adaptive immune responses, which may potentially be associated with the depletion of ILC2s." (PMID 38430390, 2024). "Moreover, IL-33 expression has been found to be upregulated within TME; tumor-initiating cells facilitate IL-33 secretion, which consecutively recruits TAMs, MDSCs, and Tregs, therefore establishing a highly suppressive milieu for immune responses and contributing to further tumor spread." (PMID 36298472, 2022). "However, considering that Th1 cells and NKT cells are downregulated in the high IL-33 tumor samples in both the primary and metastatic settings, IL-33 itself may not account for the downregulation of Th1 cells and NKT cells." (PMID 33621202, 2021). "In addition, IL-33 elevated the immunohistochemistry (IHC) staining intensity of endothelial cell marker like CD31, an indicator of neomicrovessels (i.e. blood and lymphatic vessels), which suggested that active angiogenesis and lymphangiogenesis occurred in IL-33-treated tumours." (PMID 33308251, 2020). "Additionally, the similarity in IL-33 protein levels between tumor and non-tumor tissue might be showing a low-grade inflammation in healthy tissue, that is undetected by histological analysis." (PMID 31281317, 2019).
tumor (continued). "The lack of expression of IL-33 in the metastatic A9 tumours likely contributed to their inability to support or attract ILC2s to the site of the tumour; and consequently, the microenvironment of the metastatic A9 tumours does not appear to support the development and function of ILC2s." (PMID 29440650, 2018). "Thus, our results show that the IL-33/ST2 interaction is required for SCC progression and that it is involved in a mechanism that contributes to the recruitment of CD4+ T lymphocytes, dendritic cells, and macrophages, predominantly the M2 phenotype, to the tumor microenvironment." (PMID 30112116, 2018). "Interestingly, another study showed that IL-33 does not affect the number of MDSC but can significantly reduce the differentiation of lineage-negative bone marrow progenitor cells into granulocytic MDSC in tumor-bearing mice." (PMID 30416507, 2018). "Consequently, IL-33 provides a selective pressure for ST2L-negative, oncosis-resistant cells, which may expand after HIF-1-dependent translocation to the proximal regions of tumour blood vessels, thus increasing the ratio of malignant cells." (PMID 26775708, 2016). "However, we could not rule out the possibility that sST2 inhibited tumour angiogenesis independent of IL-33 by suppressing the production of other proangiogenic factors by inflammatory cells and TAMs." (PMID 27882929, 2016). "However, the role of IL-33/IL-33R axis in neoangiogenesis and tumor necrosis is not elucidated." (PMID 26919112, 2016). "F4/80+ tumour-associated macrophages (TAMs), α-smooth muscle actin (αSMA)+ cancer-associated fibroblasts (CAFs), CD3+ lymphocytes and CD31+ tumour endothelial cells were negative for IL-33, and IL-33 was detected in some EGFP-positive cells in EGFP-P29 tumours." (PMID 26775708, 2016). "It was recently reported that FMRP does not impact tumor cell growth but facilitates immune evasion by controlling CCL7, IL-33, and PROS1." (PMID 41513619, 2026). "This was revealed by absence of therapeutic response to DAC treatment in ST2−/− tumor-bearing mice and by 3D microfluidic chip experiments showing lack of migration of ST2−/− immune cells towards DAC/IL-33 treated tumors." (PMID 40317004, 2025). "Immunofluorescence confirmed that IL-33 induced an accumulation of M2 macrophages, whereas CD163 was absent in tumor tissues of 615-line mice treated with anti-CSF1R." (PMID 38238529, 2024). "Moreover, IL-33 produced by non-tumor epithelial cells has been shown to drive colorectal cancer tumorigenesis in APCMin/+ mice, which serve as an excellent model for colorectal tumors due to a mutation in the APC gene, a significant tumor-suppressor gene in the Wnt signaling pathway." (PMID 40236667, 2024). "This phenomenon, unique to the IL-33-treated mice and absent in the control group treated with PBS, defines a specific role for ILC2s in regulating immune surveillance and tumor development." (PMID 38524132, 2024). "Similar to tumor data on ILC-2s, the effect of PD-1 on ILC-2 metabolic switch is apparent only with exogenous IL-33 priming of animals and is not apparent in the absence of IL-33 as an alarmin." (PMID 37098069, 2023). "As an antagonist of IL-33/ST2, sST2 plays a negative role in CRC tumor growth by inhibiting IL-33-mediated angiogenesis, Th1 and Th2 responses, macrophage infiltration, and M2a polarization." (PMID 36291105, 2022). "RNA-seq data also demonstrated that several genes related to adoptive immune systems which have pro-tumor action, such as TGFβ2, TGFBI, TGFBR1, TGFBR3, PLAU, IL-1β, and IL-33 are higher in Pn-positive cells than Pn-negative cells." (PMID 34680221, 2021). "Substantially elevated levels of IL‐33 and CD206 but not CD68 were observed in the tumour tissue samples than the non‐tumour tissue samples." (PMID 33305406, 2021).